SNHG32 (small nucleolar RNA host gene 32)
Synonyms: D6S57; G8; C6orf48
Gene: Long non-coding RNA gene on chromosome 6 (31,822,094 to 31,839,766, forward strand). Ensembl gene ENSG00000204387.
Gene Ontology:
Biological process: RNA processing
Cellular component: nucleolus
Diseases named in the same sentence as SNHG32 in open-access papers:
SNHG32 is named in the same sentence as 16 diseases in open-access papers, as found by Europe PMC text mining. Sharing a sentence is not in itself a finding about the gene and the disease.
SNHG32 shares sentences with these, for which no sentence is quoted: tumor (3 papers); infection (2); atherosclerosis (1); diabetes (1); glioblastoma (1); hyperlipidaemia (1); leiomyosarcoma (1); melanoma (1); prostate carcinoma (1); rhabdomyosarcoma (1); sitosterolemia (1); skin carcinoma (1); skin tumors (1); spindle cell rhabdomyosarcoma (1); Type-1 diabetes (1); Wilms tumor (1).